PDGFRB (platelet derived growth factor receptor beta)
Description:
Tyrosine-protein kinase that acts as a cell-surface receptor for homodimeric PDGFB and PDGFD and for heterodimers formed by PDGFA and PDGFB, and plays an essential role in the regulation of embryonic development, cell proliferation, survival, differentiation, chemotaxis and migration. Plays an essential role in blood vessel development by promoting proliferation, migration and recruitment of pericytes and smooth muscle cells to endothelial cells. Plays a role in the migration of vascular smooth muscle cells and the formation of neointima at vascular injury sites. Required for normal development of the cardiovascular system. Required for normal recruitment of pericytes (mesangial cells) in the kidney glomerulus, and for normal formation of a branched network of capillaries in kidney glomeruli. Promotes rearrangement of the actin cytoskeleton and the formation of membrane ruffles. Binding of its cognate ligands - homodimeric PDGFB, heterodimers formed by PDGFA and PDGFB or homodimeric PDGFD -leads to the activation of several signaling cascades; the response depends on the nature of the bound ligand and is modulated by the formation of heterodimers between PDGFRA and PDGFRB. Phosphorylates PLCG1, PIK3R1, PTPN11, RASA1/GAP, CBL, SHC1 and NCK1. Activation of PLCG1 leads to the production of the cellular signaling molecules diacylglycerol and inositol 1,4,5-trisphosphate, mobilization of cytosolic Ca(2+) and the activation of protein kinase C. Phosphorylation of PIK3R1, the regulatory subunit of phosphatidylinositol 3-kinase, leads to the activation of the AKT1 signaling pathway. Phosphorylation of SHC1, or of the C-terminus of PTPN11, creates a binding site for GRB2, resulting in the activation of HRAS, RAF1 and down-stream MAP kinases, including MAPK1/ERK2 and/or MAPK3/ERK1. Promotes phosphorylation and activation of SRC family kinases. Promotes phosphorylation of PDCD6IP/ALIX and STAM. Receptor signaling is down-regulated by protein phosphatases that dephosphorylate the receptor and its down-stream effectors, and by rapid internalization of the activated receptor.
Synonyms: PDGFR-1; CD140b; PDGFR; PDGFR1; JTK12; IBGC4; IMF1; KOGS; OPDKD; PENTT
Tractability: Small molecule: an approved drug acts on it; a high-quality ligand is known; it belongs to a druggable protein family. Antibody: a drug acting on it is in phase 2 or 3 trials; its Gene Ontology location is reachable by antibodies, with high confidence; UniProt places it where antibodies can reach, with medium confidence; UniProt predicts a signal peptide or a membrane-spanning region. PROTAC: UniProt records ubiquitination sites on it; ubiquitination databases record sites on it; its protein half-life has been measured; a small molecule that binds it is known. Other modalities: an approved drug acts on it.
Target class: TK protein kinase group; Kinase; Tyrosine protein kinase PDGFR family; Protein Kinase; Enzyme
Chemical probes: AC710, CP-673451 (high quality), HG-7-85-01 (high quality), IMATINIB, PD080975, PD082494, PD083228, PD084929, PD134526, PD134527, PD134528, PD134529, PD134530
Safety:
Unwanted effects reported when the protein is acted on. In parentheses: how it was acted on, where the effect was seen, and who reports it.
heart disease (cardiovascular system; source: Force et al. (2011))
Gene: Protein-coding gene on chromosome 5 (150,113,839 to 150,158,260, reverse strand). Ensembl gene ENSG00000113721.
Subcellular location: Cell membrane; Cytoplasmic vesicle; Lysosome lumen
Subcellular location (Human Protein Atlas): Vesicles; Golgi apparatus
Pathways (Reactome):
Signal Transduction: Downstream signal transduction; PI5P, PP2A and IER3 Regulate PI3K/AKT Signaling; PIP3 activates AKT signaling; RAF/MAP kinase cascade; Signaling by PDGF
Disease: Constitutive Signaling by Aberrant PI3K in Cancer
Gene Ontology:
Molecular function: enzyme binding; GTPase activator activity; phospholipase C activator activity; platelet-derived growth factor beta-receptor activity; platelet-derived growth factor binding; platelet-derived growth factor receptor binding; protein binding; protein kinase activity; protein kinase binding; protein tyrosine kinase activity; signaling receptor binding; vascular endothelial growth factor binding; platelet activating factor receptor activity; platelet-derived growth factor receptor activity; ATP binding; kinase activity; transmembrane receptor protein tyrosine kinase activity
Biological process: cell chemotaxis; peptidyl-tyrosine phosphorylation; platelet-derived growth factor receptor signaling pathway; platelet-derived growth factor receptor-beta signaling pathway; positive regulation of calcium-mediated signaling; positive regulation of cell migration; positive regulation of cell population proliferation; positive regulation of cell proliferation by VEGF-activated platelet derived growth factor receptor signaling pathway; positive regulation of ERK1 and ERK2 cascade; positive regulation of phosphatidylinositol 3-kinase/protein kinase B signal transduction; positive regulation of smooth muscle cell migration; positive regulation of smooth muscle cell proliferation; protein autophosphorylation; signal transduction; angiogenesis; aorta morphogenesis; cardiac myofibril assembly; cell migration involved in coronary angiogenesis; cell migration involved in vasculogenesis; cell surface receptor protein tyrosine kinase signaling pathway; metanephric glomerular capillary formation; metanephric glomerular mesangial cell proliferation involved in metanephros development; positive regulation of calcium ion import; positive regulation of chemotaxis; positive regulation of DNA biosynthetic process; and 15 more
Cellular component: focal adhesion; membrane; plasma membrane; apical plasma membrane; cytoplasm; nucleus; receptor complex; cell surface; cytoplasmic vesicle; lysosomal lumen; ruffle
Genetic constraint (gnomAD): Loss-of-function variants: 31 observed, 83.06 expected, observed/expected ratio (o/e) 0.37, 90% interval 0.28 to 0.5. The upper end of that interval is the gene's LOEUF score, 0.5, which puts it in group 2 of 6, group 1 being the genes least tolerant of losing a copy. Missense variants: 946 observed, 1,219.4 expected, observed/expected ratio (o/e) 0.78, 90% interval 0.74 to 0.82. Synonymous variants: 476 observed, 507.98 expected, observed/expected ratio (o/e) 0.94, 90% interval 0.87 to 1.01.
Homologues: Orthologues: chimpanzee PDGFRB (99% identical), macaque PDGFRB (98% identical), dog PDGFRB (90% identical), rabbit PDGFRB (90% identical), pig PDGFRB (89% identical), guinea pig PDGFRB (88% identical), rat Pdgfrb (86% identical), mouse Pdgfrb (85% identical), tropical clawed frog pdgfrb (56% identical), zebrafish pdgfrb (48% identical). Paralogues in human: PDGFRA (43% identical), CSF1R (30% identical), KIT (29% identical), FLT4 (28% identical), FLT1 (27% identical), KDR (26% identical), FLT3 (24% identical), FGFR1 (21% identical), FGFR3 (20% identical), FGFR2 (19% identical), FGFR4 (19% identical), TIE1 (17% identical), and 41 more.
Diseases named in the same sentence as PDGFRB in open-access papers:
PDGFRB is named in the same sentence as 535 diseases in open-access papers, as found by Europe PMC text mining. Sharing a sentence is not in itself a finding about the gene and the disease. The quoted sentences say what the papers report.
breast cancer (167 papers, 2005 to 2026). A primary or metastatic malignant neoplasm involving the breast. "In BRCA1-deficient breast cancer cells, deletion of PDGFRβ promoted cell death and inhibited tumorigenesis." (PMID 39780187, 2025). "In human breast cancer, high aSMA or PDGFRb+ myofibroblast infiltration was associated with poor patient prognosis, and high PDPN expression is associated with higher tumor grade." (PMID 38525245, 2024). "Another study used double immunostaining of α11 integrin and PDGFRβ in human breast cancer samples and associated normal tissues of DCIS patients." (PMID 37496657, 2023). "By subjecting wild-type and α11-deficient CAFs from PyMT mouse mammary tumors io 3D spheroid assays, we showed that the interaction between α11 and PDGFRβ in CAFs is needed for efficient PDGFRβ signaling through JNK upon PDGF-BB stimulation." (PMID 36003785, 2022). "Recently, in a large study on early-stage breast cancer, high PDGFRB expression was associated with the risk of recurrence after RT." (PMID 35406617, 2022). "We also found that in MMTV-PyMT mammary tumor specimens integrin α11 is strongly associated in breast cancer specimens with a PDGFRβ+ CAF subset and to lower degrees with PDGFRα, α-SMA, NG2 and FAP." (PMID 35378690, 2022). "Our work offers the first genetic and biochemical evidence that PDGFRβ-PKCα signaling is repressed by BRCA1, which establishes PDGFRβ-PKCα signaling as a therapeutic target for BRCA1-deficient breast cancers." (PMID 33478572, 2021). "PDGFRβ signaling plays a critical role in activating cancer-associated fibroblasts (CAFs) which facilitate breast cancer growth and progression." (PMID 33478572, 2021). "In breast cancer, while iCAFs (PDGFRB+, ACTA2-, CD34+, MCAM-) were implicated in cytotoxic T cell dysfunction of tripe-negative breast cancer, myCAFs (ecm) and myCAFs (TGFβ) were shown to be the primary resistance elements of immunotherapies." (PMID 34869001, 2021). "We also found that inhibition of PDGFR or PKCα activity efficiently killed BRCA1-deficient human breast cancer cells and that expression of BRCA1 was inversely related to that of PDGFRβ and PKCα in human breast cancer samples." (PMID 33478572, 2021). "We have recently demonstrated that integrin α11 identifies a PDGFRβ-positive subset of cancer associated fibroblasts displaying pro-tumorigenic features in breast cancer." (PMID 33014790, 2020). "High stromal PDGFRβ is associated with metastasis, larger tumour size, high histopathological grade, and shorter survival in human breast cancer." (PMID 28531107, 2017). "The result showed that the correlation between urinary PDGFRB levels and the risk of breast cancer recurrence was statistically significant (coefficient factor was −1.274, P<0.001)." (PMID 24801713, 2014). "The relationship between urinary PDGFRB and the risk of breast cancer recurrence was further estimated." (PMID 24801713, 2014). "In support of our finding a recent clinical study showed that elevated levels of stromal PDGFRβ were associated with a poor prognosis in breast cancer patients." (PMID 22608253, 2012). "Additionally, high stromal PDGFRB expression was associated with significantly shorter recurrence-free and breast cancer-specific survival." (PMID 36979654, 2023). "Moreover, high PDGFRβ expression was associated with shorter recurrence-free survival and breast cancer specific survival, mostly in pre-menopausal patients, suggesting a possible role of estrogen in regulating PDGFRβ expression and activity." (PMID 34885027, 2021). "Importantly, in human breast cancers, high stromal PDGFRβ expression is significantly associated with high histopathological grade, ER negativity, and shorter recurrence-free survival." (PMID 33478572, 2021).
breast cancer (continued). "Deficient perivascular coverage of tumor blood vessels in a PDGFRβ−/− mouse model of breast cancer resulted in recruitment of MDSCs contributing to an immunosuppressive tumor microenvironment mediated by the induction of the protumorigenic cytokine IL-6 in malignant cells." (PMID 28878242, 2017). "For example, increased expression of PDGFRβ has been associated with enhanced cell migration and invasion in breast cancer; BreastMark identifies PDGFRβ as a marker of poor prognosis and this RTK has been shown to be inhibited by imatinib in phase I clinical trials." (PMID 23820017, 2013). "PDGFRβ is expressed by both breast cancer cells and tumor-associated ECs in 69.7% of the cases." (PMID 27713269, 2010). "Our study suggests that patients with higher expression of PDGFRb might have an increased risk of any breast cancer recurrence, but due to correlation with younger age and ER negativity, a function of PDGFRb as independent prognostic marker could not be demonstrated." (PMID 33661437, 2021). "Imatinib is an inhibitor aimed at PDGFRβ tyrosine kinase receptors, and Marion T. Weigel and colleagues found that imatinib inhibits the growth and induces apoptosis of breast cancer cells." (PMID 41562694, 2026). "The two driver genes with the most interactions were PDGFRB in basal-like breast cancer and MET in thyroid cancer." (PMID 40258059, 2025). "Previous studies have demonstrated a significant correlation between increased PDGFRB expression and the prognosis of breast cancer patients." (PMID 40128057, 2025). "PDGFRα and PDGFRβ are widely expressed in fibroblasts and various cancer cells, with PDGFRβ expression in stromal cells in breast cancer correlating positively with histopathological grade and HER2 expression, but negatively with ER expression." (PMID 40230452, 2025). "Minimal co-localisation of commonly used CAF markers, such as FSP1, αSMA, and PDGFRβ, was observed in tumour stroma of pancreatic and breast cancer mouse models, highlighting the inability of these markers to represent all CAFs in isolation." (PMID 39780187, 2025). "We predicted PDGFRB as a TSG in basal-like breast cancer which is annotated to interact with 16 inhibitors and three drugs with antagonist or inhibitor interactions." (PMID 40258059, 2025). "In breast cancer, recent findings also indicate that the loss of PTPN12 phosphatase function activates several oncogenic RTKs such as MET, PDGFRb, HER2, and EGFR, positioning PTPN12 as a master regulator of protein tyrosine kinases." (PMID 38612874, 2024). "By overexpressing TWIST1, an epithelial to a mesenchymal transition transcription factor, activation of the PDGFRB promoter was observed, which leads to increased proliferation and migration in a breast cancer cell line." (PMID 39365797, 2024). "Consistent with the predictions, synthesized compounds targeting tubulin assembly, KDR, and PDGFRB displayed antiproliferative activity against a panel of cancer cell lines, including breast cancers." (PMID 38424554, 2024). "Again, BM-MSCs were not the main contributors to the population of CAFs, as the majority of the PDGFRβ+ and PDGFRβ− CAFs, in the resulting mammary tumors were tdTomato-positive and therefore derived from the host rather than the transplanted BM." (PMID 36635273, 2023). "Some of the alterations identified are drivers of different tumors and for VM formation: S1PR1 (breast cancer), PDGFRB, TIE-1 (melanoma), LOXL2 (hepatocellular carcinoma) and interestingly TCF-4." (PMID 36797281, 2023). "We performed RNA-seq sequencing of ezetimibe-treated breast cancer cells, and the results showed that ezetimibe inhibited the expression of PDGFRβ in TNBC cells." (PMID 38027998, 2023). "PDGFRβ blockade was also reported to dampen BRCA1-mediated tumorigenesis in a transgenic mouse model of breast cancer." (PMID 37294349, 2023).
breast cancer (continued). "The results showed that invasive ductal cancer (IDC) had higher densities of integrin-11 or PDGFR than DCIS tumors, which suggested that integrin α11 is mainly expressed by a subset of PDGFRβ-positive CAFs in human breast cancer." (PMID 37496657, 2023). "The presence of PDGFRβ in CAFs correlates with the clinical features and prognosis of individuals diagnosed with breast cancer." (PMID 38273859, 2023). "PDGFs and their receptors (PDGFRA and PDGFRB) are expressed in a variety of malignant tumor cells and tissues such as breast cancer and neuroendocrine tumors." (PMID 36979654, 2023). "It has been previously reported that CD44 can promote CSC traits of metastatic breast cancers by activating the PDGFRβ/Stat3 signaling pathway." (PMID 37117249, 2023). "Mechanistically, α11β1 has been shown to regulate the PDGFRβ/JNK signaling axis in breast cancer CAFs, leading to ECM remodeling and CAF-induced tumor cell invasion." (PMID 36003785, 2022). "An increase in the expression of PDGFRβ was seen in multiple tumors, including gastrointestinal tumor, lung cancer, breast cancer, hepatocellular carcinoma, and pancreatic cancer." (PMID 35637958, 2022). "PDGFRB is known to be abundantly expressed in normal stromal fibroblasts and advanced breast cancer cells." (PMID 36430911, 2022). "Previous studies have found that in breast cancer, PDGFRB+CAFs recruit CD4+CD25+FOXP3+ Treg cells, and the recruited Treg cells inhibit the activation and proliferation of CD8+T cells in the TME, thereby inducing local immunosuppression." (PMID 35967414, 2022). "The functional relevance of the CD44s isoforms has been highlighted in malignancies other than colon cancer, namely in prostate and breast cancer where it activates, among others, PDGFRβ/Stat3 and Akt signaling to promote EMT and CSC traits." (PMID 36346211, 2022). "Our study suggests breast cancer phenotypes attributed to PDGFRβ signaling can be cancer cell intrinsic." (PMID 33478572, 2021). "Analyses of the preclinical MMTV-PyMT (mouse mammary tumor virus polyoma middle tumor antigen) model and human samples unveiled the crucial role played by a subset of CAFs expressing the collagen-binding integrin α11β1 and PDGFRβ in breast cancer progression." (PMID 34131655, 2021). "PDGFRβ is abundantly expressed in normal stromal fibroblasts and in late-stage breast cancer cells, whereas PDGFs, ligands to PDGFRβ, are mainly expressed and secreted in epithelial and carcinoma cells." (PMID 33478572, 2021). "Pdgfrβ is abundantly expressed in stromal fibroblasts which also play an important role in facilitating breast cancer growth and progression." (PMID 33478572, 2021). "Implying epithelial origin, most Pdgfrβ-positive p18−/−;Brca1MGKO and p16−/−;Brca1MGKO mammary tumor cells were also positive for Ck14, an epithelial marker." (PMID 33478572, 2021). "PDGFRα/β are both upregulated in multiple tumors, and PDGFRβ is correlated with poor survival in breast cancer." (PMID 33292666, 2020). "For example, CD44 standard isoform (CD44s) is positively correlated with CSC gene signature in breast cancer, notably through PDGFRβ/Stat3 activation." (PMID 32984031, 2020). "Our study revealed that high stromal integrin α11/PDGFRβ expression is correlated with a poorer clinical outcome in breast cancer patients and that this integrin harnesses the PDGFRβ/JNK signaling pathway to promote the invasion of cancer cells." (PMID 33014790, 2020). "We found that high PDGFRβ expressing basal-like breast cancer patients (n = 421) exhibited significantly higher probabilities of relapse free survival than low PDGFRβ expressing patients (n = 197) [HR = 0.77 (0.69–1); n = 618; Logrank P = 0.049]." (PMID 30777101, 2019). "To investigate this in a clinical context, we analyzed the relationship between PDGFRβ mRNA expression and the survival of breast cancer patients using KMPlotter datasets." (PMID 30777101, 2019).